SRPRB (SRP receptor subunit beta)
Description:
Component of the signal recognition particle (SRP) complex receptor (SR) (By similarity). Ensures, in conjunction with the SRP complex, the correct targeting of the nascent secretory proteins to the endoplasmic reticulum membrane system (By similarity). May mediate the membrane association of SR (By similarity).
Synonyms: SR-beta; APMCF1
Tractability: Small molecule: a structure with a bound ligand is known. Antibody: UniProt predicts a signal peptide or a membrane-spanning region; the Human Protein Atlas places it where antibodies can reach. PROTAC: ubiquitination databases record sites on it; its protein half-life has been measured.
Gene: Protein-coding gene on chromosome 3 (133,784,023 to 133,825,772, forward strand). Ensembl gene ENSG00000144867.
Subcellular location: Endoplasmic reticulum membrane
Subcellular location (Human Protein Atlas): Plasma membrane
Pathways (Reactome):
Cellular responses to stimuli: XBP1(S) activates chaperone genes
Metabolism of proteins: SRP-dependent cotranslational protein targeting to membrane
Gene Ontology:
Molecular function: protein binding; GTP binding
Biological process: protein targeting to ER; SRP-dependent cotranslational protein targeting to membrane, signal sequence recognition
Cellular component: cytoplasm; cytoplasmic microtubule; membrane; signal recognition particle receptor complex; endoplasmic reticulum membrane
Genetic constraint (gnomAD): Loss-of-function variants: 18 observed, 25.42 expected, observed/expected ratio (o/e) 0.71, 90% interval 0.49 to 1.05. The upper end of that interval is the gene's LOEUF score, 1.05, which puts it in group 4 of 6, group 1 being the genes least tolerant of losing a copy. Missense variants: 289 observed, 299.72 expected, observed/expected ratio (o/e) 0.96, 90% interval 0.88 to 1.06. Synonymous variants: 133 observed, 128.23 expected, observed/expected ratio (o/e) 1.04, 90% interval 0.9 to 1.2.
Homologues: Orthologues: chimpanzee SRPRB (99% identical), macaque SRPRB (98% identical), rabbit SRPRB (94% identical), dog SRPRB (93% identical), pig SRPRB (91% identical), rat Tf (91% identical), mouse Srprb (90% identical), guinea pig SRPRB (85% identical), tropical clawed frog depdc5 (8% identical), zebrafish sxph (8% identical). Paralogues in human: LTF (18% identical), MELTF (11% identical), TF (10% identical).
Diseases named in the same sentence as SRPRB in open-access papers:
SRPRB is named in the same sentence as 15 diseases in open-access papers, as found by Europe PMC text mining. Sharing a sentence is not in itself a finding about the gene and the disease. The quoted sentences say what the papers report.
pancreatic ductal adenocarcinoma (2 papers, 2020 to 2024). An infiltrating adenocarcinoma that arises from the epithelial cells of the pancreas. "Furthermore, in pancreatic ductal adenocarcinoma, SRPRB was regulated by SERP1, a prognostic marker, acting on its development." (PMID 38440732, 2024).
endometriosis (1 paper, 2025). The growth of functional endometrial tissue in anatomic sites outside the uterine body. "This study employed an integrated multi-omics approach to identify and validate five core molecules (SRPRB, RBM3, INSIG2, GYG1, and FBXW2) demonstrating significant differential expression in both endometriosis and RIF, with robust diagnostic discriminatory power." (PMID 41462508, 2025). "Western blot analysis consistently demonstrated that the protein expression levels of SRPRB, RBM3, INSIG2, GYG1, and FBXW2 were significantly reduced in both endometriosis and RIF groups compared to the normal group, with statistical analysis validating these findings." (PMID 41462508, 2025).
Hyperinsulinemia (1 paper, 2021). An increased concentration of insulin in the blood. "Previous studies have also shown that SRPRB is responsible for the dephosphorylation and inactivation of Akt protein and can lead to insulin resistance in adipocytes induced by chronic hyperinsulinemia." (PMID 34094926, 2021).
liver cancer (1 paper, 2021). An epithelial or non-epithelial malignant neoplasm that arises from the liver. "The mechanism of SRPRB in the prognosis of liver cancer merits further investigation." (PMID 34094926, 2021).
tumor (3 papers, 2009 to 2024). "The outcomes of the Kruskal–Wallis test unveiled a significant correlation between high expression levels of C1orf216 and EEF1E1 (p < 0.05), high expression of SRPRB (p < 0.01), high expression of RABGGTB (p < 0.001), and larger tumor size within the HCC cohort." (PMID 38972883, 2024).
SRPRB also shares sentences with these, for which no sentence is quoted: breast carcinoma (3 papers); cancer (2); airway hyperresponsiveness (1); asthma (1); bladder cancer (1); colon carcinoma (1); glioma (1); Insulin resistance (1); melanoma (1); ovarian carcinoma (1).